LINC01229 (long independently transcribed non-coding RNA 1229)
Synonyms: TCONS_00024480
Gene: Long non-coding RNA gene on chromosome 16 (79,676,048 to 79,809,716, forward strand). Ensembl gene ENSG00000260876.
Diseases named in the same sentence as LINC01229 in open-access papers:
LINC01229 is named in the same sentence as 1 disease in open-access papers, as found by Europe PMC text mining. Sharing a sentence is not in itself a finding about the gene and the disease. The quoted sentences say what the papers report.
gout (1 paper, 2018). A condition characterized by painful swelling of the joints, which is caused by deposition of urate crystals. "LINC01229 also associates with inflammation- and gout-relevant GO terms including ‘interleukin β secretion,’ ‘T-cell differentiation,’ and ‘interleukin 2 biosynthetic process’." (PMID 30719032, 2018).